HES1 (hes family bHLH transcription factor 1)
Diseases named in the same sentence as HES1 in open-access papers (continued):
Sharing a sentence is not in itself a finding about the gene and the disease.
cervical carcinoma (9 papers, 2014 to 2025). A carcinoma arising from either the exocervical squamous epithelium or the endocervical glandular epithelium. "In a recently published study, rutin was found to cause apoptosis of cervical cancer cells by downregulation of the Notch-1 and Hes-1 genes." (PMID 36295828, 2022). "Hes-1 and Notch-1 overexpression has been associated with the progression of cervical cancer." (PMID 34440505, 2021). "Through inducing apoptosis, causing G0/G1 phase arrest, and downregulating the levels of Notch-1 and Hes-1 in the Notch signaling pathway, these findings collectively demonstrate that rutin has strong anticancer effects in human cervical carcinoma Caski cells." (PMID 41142938, 2025). "By causing apoptosis, G0/G1 phase arrest, and downregulating the levels of Notch-1 and Hes-1 of the Notch signaling pathway, rutin demonstrated strong anticancer effects in human cervical carcinoma Caski cells." (PMID 41142938, 2025). "Hes1 also promotes cervical cancer cell proliferation and inhibits differentiation via Hash1 downregulation, whereas reduced Hes1 mRNA expression induces apoptosis in these cells." (PMID 40755759, 2025). "Rutin has recently been demonstrated to regulate Notch-1 and Hes-1 mRNA levels in cervical cancer cells." (PMID 36295828, 2022). "Altogether, these results showed that rutin showed potent anticancer effects in human cervical cancer Caski cells by triggering apoptosis, G0/G1 phase arrest, and downregulating the level of Notch-1 and Hes-1 of the Notch signaling pathway." (PMID 34440505, 2021). "Results indicated that rutin treatment significantly downregulated the mRNA expression of Notch-1 and Hes-1 genes of Notch signal transduction in human cervical cancer Caski cells." (PMID 34440505, 2021). "In adherent cervical cancer cells FTS co-precipitated with Notch1/cleaved Notch1/Hes1, suggesting FTS molecular interaction with Notch molecules." (PMID 34765546, 2021). "It indicates a potential regulatory role of HPVE6 in maintenance of cervical cancer stem cells through Hes1 expression." (PMID 29460395, 2018). "Therefore, in this study, we performed several in vitro assays to gain detailed insight about the apoptotic inducing effect of rutin as well as its modulatory effect on Notch-1 and Hes-1 in cervical cancer cells." (PMID 34440505, 2021). "Formation of spheroids is a hallmark of cancer stem cells, therefore in the present study, we evaluated spheroid formation in the cervical cancer cells and compared expression levels of Notch and its target protein Hes1, in addition to cancer stem cell markers." (PMID 34765546, 2021). "In a cervical cancer model, overexpression of the HPV oncoprotein E6 can maintain the stem-cell phenotype and stemness of CSCs through upregulation of Hes1, and short interfering RNA (siRNA) silencing of E6 or Hes1 leads to redifferentiation loss of self-renewability/stemness of CSCs." (PMID 36560828, 2022). "Moreover, Hes-1 and Hes-5 are positively associated with various prognostic factors in early-stage cervical carcinoma, suggesting that both Hes-1 and Hes-5 could be useful biomarkers to predict poor prognosis in patients with cervical carcinoma." (PMID 24899581, 2014). "The co-localization of Notch1/cleaved Notch/Hes1 and FTS spectacles the importance of FTS in mediating the Notch signaling in cervical cancer cells." (PMID 34765546, 2021). "The small subpopulation of cervical cancer stem‐like cells (CaCxSLCs) showed spheroid forming ability and expressed pluripotency, quiescence and self‐renewal markers with high expression of HPVE6 and Hes1." (PMID 29460395, 2018).
colitis (9 papers, 2013 to 2024). Inflammation of the colon. "Additionally, loss of Notch activation, and subsequent down-regulation of Hes-1 was shown to lead to colitis and adenocarcinoma, in a fucosylation deficient (Fx-/-) mouse model." (PMID 30323897, 2018). "In addition, the mRNA expression of Notch1 and Hes1 was assessed in different H. pylori–associated gastrointestinal diseases including gastritis, duodenal ulcer, gastritis with duodenal ulcer, and gastritis with colitis." (PMID 33224898, 2020). "The present study, along with previous works, showed an activated Notch-Hes1 pathway in TNF-α-treated Caco-2 cells or mice with DSS-induced colitis; however, the activation of the Notch pathway triggered by inflammation failed to rescue TJ injury." (PMID 39130644, 2024). "Under colitis conditions, we found that VD deficiency or VDR deletion significantly suppressed colitis-induced N1ICD and Hes1 stimulation." (PMID 39130644, 2024). "Consistently, along with ameliorated symptoms and histological damage, mice subjected to DSS-induced colitis receiving 5% red raspberry displayed a greater goblet cell density and increased mRNA levels of Muc2 and Klf4, and HES1 protein content." (PMID 35334805, 2022). "Our previous study has shown that number of Hes1+ve cells significantly increase in the colitic mucosa of DSS-colitis mice, and also in ulcerative colitis patients, indicating that the canonical Notch pathway is activated in those cells." (PMID 24860699, 2014). "However, Hes1 expression between the upper gastrointestinal inflammation group and the colitis group was comparable." (PMID 33224898, 2020). "In addition, mice with an epithelial-specific defect leading to reduced Hes1 expression were recently shown to spontaneously develop colitis." (PMID 23418447, 2013). "Thus, mRNA expression of Notch1 and Hes1 was examined in the CD4+ T cells from patients with different H. pylori–associated gastrointestinal tract inflammation including gastritis, duodenal ulcer, gastritis with duodenal ulcer, and gastritis with colitis." (PMID 33224898, 2020). "Interestingly, in 2.5% DSS-induced colitis mice, we found that both the fluorescence intensity and nuclear translocation of N1ICD and Hes1 increased, suggesting the activation of Notch signaling under DSS-treatment conditions." (PMID 39130644, 2024). "Double staining with Hes1 confirmed that a rare population of Dll1+ve IECs, as well as the dominant Dll4+ve IECs clearly located adjacent to Hes1+ve IECs within the elongated crypts of the DSS-colitis mice." (PMID 24860699, 2014).
lymphoma (9 papers, 2009 to 2023). A malignant (clonal) proliferation of B- lymphocytes or T- lymphocytes which involves the lymph nodes, bone marrow and/or extranodal sites. "Consistent with this, and as an example, we observed that the levels of expression of the canonical ICN1 target genes Hes1, Dtx1, and Ptcra are quite similar in the lymphoma cells from both mouse models." (PMID 35895495, 2022). "Real-time RT-PCR confirmed that Notch1, Notch3, Hes1 and Myc mRNA levels were upregulated in Lck-Dlx5 lymphomas, when compared with those of WT thymic T-cells and Lck-MyrAkt2 lymphomas." (PMID 28122332, 2017). "Overexpression of the active forms of Notch receptors (ICN1-4) or Notch downstream target gene hairy and enhancer of split-1 (HES1) in human B-cell leukemia/lymphoma can lead to apoptosis." (PMID 28580304, 2017). "Immunohistochemistry also confirmed that Notch1, Notch3, Hes1, Myc and phospho (active)-Akt are upregulated in primary and metastatic lymphomas from Lck-Dlx5 mice." (PMID 28122332, 2017). "When both Hes1 and Id1 are expressed in thymocytes, lymphomas develop rapidly in all animals examined." (PMID 19688092, 2009). "We have also demonstrated that Hes1 expression acts synergistically with Id1 to promote lymphoma development." (PMID 19688092, 2009). "Further analysis of this panel of lymphomas showed that the expression levels of Hes1 and Deltex1, two target genes of Notch1 signaling, were enhanced in all tumor samples compared to the control samples, again demonstrating that both the Wnt and Notch pathway are involved in full lymphomagenesis." (PMID 23185135, 2012). "However, Hes1 transgenic mice develop lymphomas with a much longer latency and with a lower frequency compared to Notch1 or Notch3 expressing animals." (PMID 19688092, 2009). "Constitutive activation of Notch is known to cause T cell leukemia or lymphoma but whether Hes1 has any oncogenic activity is not known." (PMID 19688092, 2009). "Therefore we examined the mRNA levels of the lymphoma-related proto-oncogenes involved in the Notch-1 signal pathway, including Notch-1, DLL1/4, Hes-1, PTEN and c-Myc in the liver tissues of individual animals." (PMID 23145171, 2012). "In addition, these cells had higher levels of the transcription factor Hes1 suggesting that NOTCH signalling might play a role in malignant transformation in GATA3-overexpressing cells, presumably via c-MYC, which is a direct target of NOTCH1 in T lymphoblastic leukaemia/lymphoma." (PMID 35681778, 2022).
medulloblastoma (9 papers, 2009 to 2025). A malignant, invasive embryonal neoplasm arising from the cerebellum. "In medulloblastoma, miR-199b-5p directly targets Hes1 mRNA to inhibit its expression, thereby suppressing the proliferation of tumor stem cells." (PMID 40755759, 2025). "miR-199b-5p impaired CSCs in medulloblastoma by regulating Hes Family BHLH Transcription Factor 1 (HES1)." (PMID 38360723, 2024). "Direct stimulation of Hes1 by SHH would be clinically relevant as it would limit the potential for NOTCH-pathway inhibitors to alter medulloblastoma growth." (PMID 31863004, 2019). "Consistent with a direct mechanism, SMOM2-mediated SHH hyperactivation clearly correlated with increased Hes1 expression, as Hes1+ cells were markedly enriched in M-Smo medulloblastomas compared to WT P7 cerebella." (PMID 31863004, 2019). "We analyzed transcriptomic data from human medulloblastomas to determine whether HES1 and MYOD1 are frequently expressed." (PMID 31863004, 2019). "miR-199b-5p expression correlates with metastasis spread in medulloblastoma targeting transcription factor HES1, an effector of the Notch pathway." (PMID 24040069, 2013).
colon adenocarcinoma (7 papers, 2013 to 2025). "Finally, Gao and coworkers have shown that HES1 is upregulated in poorly-differentiated colon adenocarcinoma, compared with well-differentiated tumors; HES1 mRNA expression was increased in the majority of tumor samples, compared to the corresponding normal colon tissue." (PMID 29652830, 2018). "In colon adenocarcinoma, the upregulation of Hes1 is positively correlated with the transcription factor ETV4, which binds to the Hes1 promoter sequence and activates its transcription." (PMID 40755759, 2025). "We found a bacterial regulation of the transcription factors Hes1, Hath1 and KLF4 in the colon adenocarcinoma cell line LS174T, especially by E. coli K-12 and E. coli Nissle 1917." (PMID 23418447, 2013).
psoriasis (7 papers, 2018 to 2025). An autoimmune condition characterized by red, well-delineated plaques with silvery scales that are usually on the extensor surfaces and scalp. "We confirmed that HES1 is significantly decreased in the epidermis of psoriasis patients and IMQ-induced mouse model, which is probably due to the interaction between Wnt5a and Notch141." (PMID 36535970, 2022). "Hes1 was also reported to regulate IL-17A+γδ+ T cell expression and IL-17A secretion in mouse psoriasis-like skin inflammation." (PMID 36535970, 2022). "Further studies will be needed to determine the exact HES1-binding mode of l-menthol and the mechanism of varied HES1 expression from different cell types in psoriasis." (PMID 36535970, 2022). "Prof. Honglin Wang’s team describes L-menthol for treating models of psoriasis and uncovers the dysfunctional HES1- IGBP1-PP6 axis in psoriasis pathology by using L-menthol as a probe." (PMID 36535970, 2022). "PV patients presented distinct Th17/Treg immune imbalance and highly expressed Notch1 and Hes-1 mRNA levels, which were positively correlated with psoriasis area and severity index (PASI) and the ratios of Th17/Treg and RORγt/Foxp3." (PMID 29686529, 2018). "Thus, we identified HES1 as a druggable target for psoriasis by using l-menthol as a molecular probe." (PMID 36535970, 2022). "To further investigate whether HES1 upregulation suppressed psoriasis pathology, we injected a Hes1-expressing adeno-associated virus serotype 9 (AAV-Hes1) intracutaneously to increase Hes1 in the epidermis of IMQ-induced mice." (PMID 36535970, 2022). "Taken together, HES1 is decreased in the psoriatic epidermis and might be a therapeutic target of psoriasis." (PMID 36535970, 2022). "However, epidermal-specific deletion of Hes1 exacerbated the skin inflammation in the IMQ-induced mouse model of psoriasis." (PMID 36535970, 2022). "Furthermore, immunohistochemical analyses showed that HES1 was dramatically decreased in the epidermis of psoriasis patients compared with that of healthy controls." (PMID 36535970, 2022). "So combination of in vitro and in vivo results, we may conclude that Notch-Hes1 signaling can express its effects in the pathogenesis of psoriasis by regulating IL-17A+γδ+T cells." (PMID 32454795, 2020). "In this study, the elevated expression of Notch1 and its target gene Hes-1 was demonstrated in peripheral CD4+ T cells of PV patients and positively associated with psoriasis area and severity index, which indicates that Notch1 signaling participates in the development and progress of PV." (PMID 29686529, 2018). "Next, we questioned whether HES1 was a potential drug target for psoriasis." (PMID 36535970, 2022). "Thus, HES1 upregulation suppressed the psoriasis-like skin inflammation in mice." (PMID 36535970, 2022). "In summary, the current study may suggest that Notch-Hes1 signaling is participated in the pathogenesis of psoriasis by regulating IL-17A+γδ+T cell expression and IL-17A secretion, and blocking Notch-Hes1 signaling may be a new strategy for immunotherapy of psoriasis." (PMID 32454795, 2020). "The upregulation of HES1 restored PP6 expression in inflamed keratinocytes and mitigated psoriasis-like skin inflammation." (PMID 36535970, 2022). "Taken together, Hes1-deletion in keratinocytes decreases Pp6 and exacerbates IMQ-induced psoriasis-like skin inflammation." (PMID 36535970, 2022). "Therefore, taking into the literature reports and our research results into account, we may conclude that Notch-Hes1 signaling can regulate the two major sources of IL-17A, Th17 cells, and IL-17A+γδ+T cells, in psoriasis through different transcription factor pathway, respectively." (PMID 32454795, 2020). "Midkine is a heparin-binding growth factor broadly expressed in inflammatory diseases; recent studies have shown that MK regulates VEGF-A expression via the Notch2/HES1/JAK2-STAT5A signaling pathway, thereby exerting critical effects on angiogenesis in psoriasis." (PMID 40959079, 2025).
endometrial cancer (6 papers, 2020 to 2025). Primary or metastatic malignant neoplasm involving the endometrium (mucous membrane that lines the endometrial cavity). "On the other hand, AR was required for FOXA1-enhanced Notch pathway activation in endometrial cancer cells, increasing Notch1 and HES1 expression." (PMID 33167316, 2020). "It is highly expressed in endometrial cancer and can regulate the endometrial cancer cell cycle and cell apoptosis by interacting with the stem cell-related factor Notch-1 and its downstream targets (transcription factor Hes-1 and cell cycle regulator WAF1/CIP1)." (PMID 33747079, 2021). "Endometrial cancer studies reveal crosstalk between Notch/Hes1 and Wnt/β-catenin in differentiation: GSK-3β inhibition simultaneously upregulates Hes1 and β-catenin, driving cancer cell proliferation/migration." (PMID 40755759, 2025). "In the poorly differentiated endometrial cancer cell line HEC-50B, an autocrine FGF/FGFR signaling stimulates Hes1 expression and cell proliferation." (PMID 40755759, 2025). "In endometrial cancer and TNBC, there exists crosstalk between the Notch/Hes1 and Wnt/β-catenin pathways, and dual targeting of these pathways represents a potential therapeutic direction." (PMID 40755759, 2025). "Recently, autocrine FGFR activation has been correlated with HES1 (hairy and enhancer of split-1) expression and AKT-dependent cell proliferation in endometrial cancers insensitive to Notch inhibition." (PMID 34830951, 2021).
non-small cell lung carcinoma (6 papers, 2009 to 2025). A group of at least three distinct histological types of lung cancer, including non-small cell squamous cell carcinoma, adenocarcinoma, and large cell carcinoma. "Recent studies of delta-tocotrienol on non-small cell lung cancer discovered that the anticancer activity induced by delta-tocotrienol is associated with its ability to decrease Notch-1, Hes-1, Survivin, MMP-9, VEGF, and Bcl-XL expressions, with additional decrease of binding activity in NF-κB-DNA." (PMID 25480449, 2014). "Studies have shown that the overactivity of Notch and the increased expression of Notch1 and Hes1 proteins may indicate a poor prognosis of non-small cell lung cancer." (PMID 38544826, 2024). "Taken together, these results showed that SOX1 is frequently downregulated by promoter hypermethylation in non-small-cell lung cancer, which may lead to aberrant activation of HES1." (PMID 37190139, 2023). "Conversely, non-small cell lung cancer expresses lower levels of E2F-1 and higher levels of Hes-1, indicating that Hes factors may be important in E2F-1 regulation in these cancers as well." (PMID 19891787, 2009). "Similarly, in non-small cell lung cancer (NSCLC) cells, ST6GAL1 silencing suppressed migration and invasion in vitro and in vivo, through inactivation of the Notch1/Hes1/MMPs pathway." (PMID 33921986, 2021).
atherosclerosis (5 papers, 2017 to 2024). A disease characterized by the build-up of fatty material and calcium deposition in the arterial wall resulting in partial or complete occlusion of the arterial lumen. "In that study, they showed that decreased HES-1 in endothelial cells within atherosclerosis plaque region resulted in an increase in OPN levels followed by increased angiogenesis." (PMID 32694555, 2020). "Since this investigation revealed that Hes-1 was downregulated in atherosclerotic plaques, the regulation of Hes-1 during atherosclerosis formation and development was further investigated." (PMID 28420872, 2017). "Although less is known about the role of Hes-1 in the immune response and atherosclerosis, as compared to VEGF and OPN, the results of the present study identified Hes-1 as a novel regulator in atherosclerosis, especially intraplaque angiogenesis." (PMID 28420872, 2017). "It has been reported that HES1 up-regulation under oxidative stress contributes to pathogenesis of multiple diseases, including endothelial cell injury in atherosclerosis and hypertension, neuronal cell apoptosis in Alzheimer's disease, and myocardial damage following ischemia and reperfusion." (PMID 28423527, 2017). "Since this investigation revealed that Hes-1 was downregulated, while OPN was upregulated, in atherosclerotic plaques, it was hypothesized that OPN was also regulated by Hes-1 during atherosclerosis formation and development." (PMID 28420872, 2017). "Therefore, restoring Hes-1 expression and inhibiting OPN expression may be a promising strategy to prevent vulnerable plaque formation in patients with atherosclerosis." (PMID 28420872, 2017).